AHR (aryl hydrocarbon receptor)
Diseases named in the same sentence as AHR in open-access papers (continued):
Sharing a sentence is not in itself a finding about the gene and the disease.
meningioma (5 papers, 2020 to 2023). A generally slow growing tumor attached to the dura mater. "The exposure of the meningioma cell lines to chemically induced hypoxia increased the level of AhR mRNA ninefold as compared with the control cultured cells but did not alter the mRNA level of ARNT and of an AhR target gene (CYP1B1)." (PMID 37305351, 2023). "Because the NcoA2 inhibits proteins of the bHLH/PAS family, such as HIF-1α, ARNT, and AhR, it is likely that in the molecular processes of meningioma ischemic hypoxia, AhR signaling probably plays a more important role than the HIF-1α pathway does." (PMID 37305351, 2023). "To date, the potential crosstalk between AhR and hypoxia pathways in meningioma cells remains to be elucidated." (PMID 37305351, 2023). "In this work, the status of HIF-1α- and AhR-dependent signaling pathways was investigated in World Health Organization (WHO) grade 1 meningioma and patient-derived tumor primary cell culture under hypoxic conditions." (PMID 37305351, 2023). "Our findings show active functioning of AhR signaling in meningioma tissue of patients with tumor embolization and crosstalk between HIF-1α and AhR signaling in meningeal cells under hypoxia." (PMID 37305351, 2023). "A study on the AhR-dependent signaling pathway in human meningiomas showed that its components are enhanced in these tumors." (PMID 32325928, 2020). "The level of AhR mRNA is higher in meningioma tissue than in the corresponding normal tissue and higher in more malignant tumors, and AhR is more abundantly localized in the nucleus, thus indicating its activation." (PMID 32325928, 2020). "The inhibitory effect of meningioma embolization on the expression of AhR pathway genes and its regulator may have a long-term therapeutic effect on meningioma cells." (PMID 37305351, 2023). "Consequently, any decrease in AhR expression in meningioma cells, for example, as a consequence of embolization, can reduce the chances of tumor growth and progression." (PMID 37305351, 2023). "As follows from the available literature data, AhR contributes to the progression of meningioma." (PMID 37305351, 2023). "It is possible that hypoxia in meningioma cells—depending on the conditions of its implementation and on the cellular microenvironment—can lead either to the depletion or to accumulation of key coregulatory proteins necessary for the execution of the AhR signaling pathway." (PMID 37305351, 2023). "Consequently, any reduction in AhR expression in meningiomas will have a therapeutic effect." (PMID 37305351, 2023). "This notion is confirmed by upregulation of cyclophilin D in all classes of meningiomas, and this protein participates in the formation of high-permeability pores in mitochondria during apoptosis, and a decrease in the amount of the c-Fos protein regulated by AhR." (PMID 32325928, 2020). "It has been demonstrated that AhR signaling pathway components such as AhR and ARNT (also known as HIF-1β) were activated as meningioma malignancy progresses from low to high." (PMID 37305351, 2023). "According to our examination of mRNA expression in patient-derived meningioma primary cells, during the hypoxia induced by CoCl2, in addition to HIF-1α activation, there is AhR upregulation." (PMID 37305351, 2023). "The decrease in AhR and HIF-1α mRNA levels in embolized meningiomas did not lead to a change in either HIF-1α or AhR protein amounts, thereby indicating a sufficiently high constitutive level of these proteins." (PMID 37305351, 2023). "mRNA expression of HIF-1α, AhR, ARNT, and HIF-1α and AhR target genes did not change when meningioma cells were incubated with B[a]P (AhR agonist)." (PMID 37305351, 2023). "Besides, in meningiomas, compared with the normal tissue and with increasing tumor malignancy (grade I, II, III), the regulation of genes of AhR-dependent signal transduction, e.g., ARNT, aldehyde dehydrogenase 1A3, and CYP1A1, is enhanced." (PMID 32325928, 2020).
meningioma (continued). "The decrease in AhR and HIF-1α mRNA levels in embolized meningiomas did not alter either HIF-1α or AhR protein amounts, thereby indicating a sufficiently high constitutive level of these proteins." (PMID 37305351, 2023). "At the same time, mRNA levels of AhR, ARNT, and NcoA2 in the meningiomas subjected to hypoxia as a result of the embolization were statistically significantly lower than those in the nonembolized meningiomas." (PMID 37305351, 2023). "As revealed by our analysis of mRNA expression in samples of meningioma tissue subjected to hypoxic ischemic preconditioning, the expression of HIF-1α and its target genes (VEGF-A, c-Myc, and GLUT1) is not affected by this procedure, whereas AhR, ARNT, and NcoA2 expressions significantly decreases." (PMID 37305351, 2023). "Therefore, the hypoxia developing in benign meningioma as a consequence of endovascular embolization may interfere with the AhR signaling pathway at the level of AhR and ARNT mRNA expressions, and this effect does not depend on the histological structure of the meningioma." (PMID 37305351, 2023).
myocardial ischemia (5 papers, 2018 to 2024). A disorder of cardiac function caused by insufficient blood flow to the muscle tissue of the heart. "Activation of the AhR pathway is associated with myocardial ischemia–reperfusion injury through the regulation of mitochondrial oxidative stress and apoptosis." (PMID 37749614, 2023). "In a model of myocardial ischemia based on the occluded left anterior descending artery, it has been found that acute myocardial ischemia can result in substantial expression of AhR in the necrotic myocardium, activate AhR, and induce inflammation." (PMID 39000041, 2024). "The use of an AhR antagonist can attenuate myocardial injury in the rat myocardial ischemia–reperfusion model." (PMID 37749614, 2023). "A recent study found that flavonoids capable of inhibiting AhR have a dual character in myocardial ischemia-reperfusion injury, either protection or deterioration." (PMID 29984241, 2018). "While there are inconsistencies in the studies, AhR appears to be a significant mediator in myocardial ischemia-reperfusion injury." (PMID 29984241, 2018). "Previous studies have reported that in the myocardial ischemia model with OLAD, AHR is abundantly expressed in necrotic myocardium and it is shown that acute myocardial ischemia can activate AHR and induce inflammation." (PMID 36879035, 2023).
non-alcoholic steatohepatitis (5 papers, 2021 to 2024). "In methionine‐choline‐deficient high‐fat diet‐induced nonalcoholic steatohepatitis (NASH), paeoniflorin reduces inflammation by inhibiting the NLRP3 inflammasome and activating the AhR pathway." (PMID 39568773, 2024). "In non-alcoholic steatohepatitis (NASH) mice, paeonol can increase the levels of indole-3-acetic acid, subsequently activating the AhR and inhibiting NLRP3 inflammasome activation." (PMID 39334766, 2024).
oral cancer (5 papers, 2013 to 2025). "AhR antagonists have been proven to be antioncogenic roles in several cancers, including lung, head and neck, and oral cancers etc.." (PMID 35002727, 2021). "The flavone baicalein induced G1 phase arrest in oral cancer cells by enhancing the degradation of CDK4 (cyclin-dependent kinase) and cyclin D1, and activating AhR (aryl hydrocarbon receptor)." (PMID 23857227, 2013).
pancreatic adenocarcinoma (5 papers, 2020 to 2023). "Although direct data are missing for the effects of indole-derivatives in pancreatic adenocarcinoma, the invasive behavior of pancreatic adenocarcinoma cells can be modulated through the selective AHR modulators, Omeprazole and Tranilast." (PMID 32344895, 2020). "While there is a lack of direct experimental data on the effects of indole derivatives in pancreatic adenocarcinoma, one study demonstrates that selective AHR modulators, such as omeprazole and tranilast, can effectively modulate the invasive behavior of pancreatic adenocarcinoma cells." (PMID 37370753, 2023).
parasitemia (5 papers, 2019 to 2025). "Generally, blocking the IDO enzyme in vivo and experiments with AhR knockout mice demonstrate an essential role of these molecules in reducing parasitemia." (PMID 40726977, 2025). "While the role of AHR has been explored in several viral, bacterial, and parasitic infections, its regulation in Cb pathogenesis remains unstudied." (PMID 39711545, 2024). "It is also possible that AHR has distinct roles in early and acute infection, but the effects of increased parasitemia overshadow other AHR-dependent phenotypes." (PMID 33021470, 2020). "While we hypothesized that AHR functions primarily during acute infection, Ahr-/- mice develop increased parasitemia relative to control mice as early as 4 DPI." (PMID 33021470, 2020). "Thus, a simple model suggests that the increased parasitemia in Ahr-/- mice leads to increased hemolysis, in turn causing heme overload and AKI; AHR only functions to control parasite load." (PMID 33021470, 2020). "Therefore, during Pc infection, AHR in radioresistant cells is necessary to promote survival, limit parasitemia, control plasma heme, and prevent AKI." (PMID 33021470, 2020). "Therefore, AHR is necessary in Tek-expressing, radioresistant cells for survival, control of parasitemia, and limiting AKI during Pc infection." (PMID 33021470, 2020). "Chimeric mice lacking AHR in radiosensitive cells (- → +) had equivalent survival and parasitemia to wild-type chimeric mice (+ → +)." (PMID 33021470, 2020). "In contrast, mice lacking AHR in radioresistant cells (+ → - and - → -) succumbed to infection and developed higher parasitemia relative to + → + mice." (PMID 33021470, 2020). "Thus, strong AhR activation with TCDD was effective to regulate inflammation in T. cruzi infected B6 mice, but the TCDD-induced immunosuppression contributed to parasite replication, and the treatment resulted in increased parasitemia and death of the treated mice." (PMID 30984194, 2019).
pneumonia (5 papers, 2020 to 2024). An acute, acute and chronic, or chronic inflammation focally or diffusely affecting the lung parenchyma, caused by an infection in one or both of the lungs (by bacteria, viruses, fungi, or mycoplasma.). "We sought to investigate the role of AhR in indole and probiotic mediated mitigation of alcohol-associated pneumonia, by treatment with the AhR inhibitor CH-223191." (PMID 34426641, 2021). "We revealed that AHR expression was also lowered in patients with pneumonia (p < 0.001), suggesting potential links to impaired local pulmonary immunity and an increased susceptibility to infection." (PMID 38932276, 2024). "Interestingly, AHR expression was significantly lower in subjects with pneumonia (p = 0.001) compared to controls." (PMID 38932276, 2024). "Manipulation of TGFb or AhR signaling pathways alters pneumonia outcomes in alcohol-fed mice." (PMID 37886455, 2023). "As AHR expression is higher in bronchoalveolar MAIT cells compared to matched circulating cells in children with pneumonia, further work should explore specifically whether tissue MAIT cells are selectively regulated by AhR in a similar manner to other IL-22 producing cells in particular." (PMID 33329559, 2020). "Specifically, AhR inhibition does not impair the trafficking of immune cells to the lung in response to pneumonia in animals that received probiotic supplementation." (PMID 34426641, 2021).
preeclampsia (5 papers, 2017 to 2025). Preeclampsia is a hypertensive disorder of pregnancy that is characterized by new-onset hypertension with proteinuria presenting after 20 weeks of gestation, and depending on mild or severe forms may initially present with severe headache, visual disturbances, and hyperreflexia. "AhR gene polymorphisms are associated with the development of preeclampsia in the Chinese population." (PMID 41169884, 2025). "Our results suggest that the development of preeclampsia is associated not only with reduced expression of AhR in the placenta but also with reduced efficiency of AhR activation." (PMID 41169884, 2025). "One of these pathways is the activation of AhR, and our results show the role of AhR on sFlt-1, which is an essential antiangiogenic factor associated with preeclampsia." (PMID 38248350, 2024). "One previous theory stated that the underlying mechanism of preeclampsia, which is a shallow placentation followed by abnormal arteriole remodeling, is compensated by the activation of AhR with smoking." (PMID 38248350, 2024). "This study offers insights into the potential role of AhR on antiangiogenic sFlt-1 associated with preeclampsia." (PMID 38248350, 2024). "Therefore, we suggest that AhR gene polymorphism is associated with the development of preeclampsia and that rs713150G is a protective factor against disease development." (PMID 41169884, 2025). "We first explored the associations of 4 TagSNPs in the AhR gene with preeclampsia." (PMID 41169884, 2025). "The activation of AhR might have a similar effect of risk reduction on preeclampsia." (PMID 38248350, 2024). "Our previous study revealed decreased AhR expression and nuclear translocation in the placentas of women with preeclampsia." (PMID 41169884, 2025). "This corresponds with the results obtained in our aforementioned study: Compared with control group, the frequency of rs713150G was lower in the preeclampsia group, and the expression level of AhR in the placenta was also significantly reduced." (PMID 41169884, 2025). "We subsequently detected the mRNA and protein expression levels of AhR in the placenta maternal surface from patients with preeclampsia and normal pregnant women." (PMID 41169884, 2025). "Compared with those from normal pregnant women, placental tissues from women with preeclampsia presented significant decreases in AhR mRNA expression (0.68), total AhR protein expression (0.44) and nuclear AhR protein expression (0.66)." (PMID 41169884, 2025). "The results revealed that the relative expression levels of AhR mRNA, total AhR protein, and nuclear AhR protein in the placental samples from women with preeclampsia were significantly lower than those in placental samples from normal pregnant women." (PMID 41169884, 2025). "This relationship between the role of sFlt-1 and AhR aided in understanding why smoking decreased the incidence of preeclampsia after exposure to cigarette smoke." (PMID 38248350, 2024). "Since smoking has a protective role in preeclampsia, there seems to be a link between the abundant expression of AhR in the placenta and its role in preeclampsia." (PMID 38248350, 2024). "Here, we show the expression of different angiogenic factors related to preeclampsia under the influence of cigarette smoke and the role of the AhR utilizing a smoking mouse model." (PMID 38248350, 2024). "Compared with individuals who carried the G allele, individuals who did not carry the G allele present lower expression of AhR in the placenta, and lower AhR expression is positively correlated with the development of preeclampsia." (PMID 41169884, 2025). "In addition, quantitative real-time PCR and western blotting were used to detect the expression of AhR in placental tissues from 21 patients with preeclampsia and 20 healthy controls." (PMID 41169884, 2025).
preeclampsia (continued). "Low expression or inhibition of AhR activity inhibits the AhR signalling pathway and may participate in the development of preeclampsia by inhibiting angiogenesis." (PMID 41169884, 2025). "We also compared the ratio of nuclear AhR protein to total AhR protein in placental tissues between the two groups, and the ratio was significantly lower in the preeclampsia group (control vs. preeclampsia: 0.680 ± 0.085 vs. 0.251 ± 0.034, t = 4.681, P = 0.003)." (PMID 41169884, 2025). "Moreover, the ratio of nuclear AhR to total AhR in the placental samples from women with preeclampsia was significantly lower than that in placental samples from normal pregnant women." (PMID 41169884, 2025). "There may be other components of cigarette smoke that alleviate the preeclampsia phenomenon, such as AhR activation." (PMID 38248350, 2024). "Herein, we focused on AhR to define the role of smoking in pregnancy and preeclampsia." (PMID 38248350, 2024). "The activation of AhR could lead to enhanced trophoblastic invasion and alleviate preeclampsia." (PMID 38248350, 2024). "In addition, it may be possible to invent a new treatment strategy for preeclampsia using AhR activation." (PMID 38248350, 2024). "Among the 4 TagSNPs in the AHR gene passed the HWE test, the frequency of rs713150G in the preeclampsia group was lower than that in the control group (OR = 0.467, 95% CI = 0.286–0.763; P = 0.002)." (PMID 41169884, 2025). "Therefore, it is speculated that mitigating the adverse effects of smoking with ingredients such as green tea catechins while simultaneously stimulating the AhR action of smoking could ultimately contribute to finding a method to treat conditions like preeclampsia during pregnancy." (PMID 38248350, 2024).
pulmonary arterial hypertension (5 papers, 2018 to 2024). Pulmonary arterial hypertension (PAH) is a group of diseases characterized by mean pulmonary artery pressure >20 mmHg and elevated pulmonary arterial resistance leading to right heart failure. "This detrimental effect of AhR activation on endothelial function has also been demonstrated in studies of pulmonary arterial hypertension." (PMID 37686342, 2023). "This AhR antagonist has also been reported to reverse experimental pulmonary hypertension induced by Sugen 5146 in rats." (PMID 35743162, 2022). "AhR is reported to be a major participant in the pathogenesis of such cardiovascular pathologies as myocarditis, hypertension, coronary heart disease, and pulmonary arterial hypertension." (PMID 35743162, 2022). "Studies examining the effect of the suppression of AhR in combination with suppression of HIF-1α in pulmonary arterial hypertension could prove to be useful." (PMID 29984241, 2018). "Therefore, AhR could be a potential drug target for the treatment of pulmonary arterial hypertension." (PMID 29984241, 2018).
thrombosis (5 papers, 2018 to 2025). "Thus, it would be critical to explore the role of AHR in the predisposition of thrombosis." (PMID 38226819, 2024). "Moreover, the prothrombotic effect of Kyn on endothelial cells and venous thrombosis models via AHR has also been demonstrated." (PMID 36359257, 2022). "Both AHR inhibitor and STUB-1 activator significantly mitigated IS and uremic serum-mediated thrombosis in flow loops coated with vSMCs, in a FeCl3-induced carotid artery injury model in the setting of CKD, and in an IS-specific solute model." (PMID 32887404, 2020). "This mechanistic link is supported by clinical data indicating that patients with AVF thrombosis exhibit higher AHR activity than those without thrombosis." (PMID 41003499, 2025). "Participants with subsequent arteriovenous thrombosis had significantly higher levels of indoxyl sulfate and Kyn, and increased AHR and TF activity compared to those without thrombosis." (PMID 36359257, 2022). "CKD patients with arteriovenous thrombosis have a significant greater activity of AHR and TF than those without thrombosis." (PMID 30322010, 2018).